ADAR (adenosine deaminase RNA specific)
Diseases named in the same sentence as ADAR in open-access papers (continued):
Sharing a sentence is not in itself a finding about the gene and the disease.
viral infection (continued). "A number of studies have demonstrated the involvement of the ADAR proteins and A-to-I editing during viral infection." (PMID 26437436, 2015). "ADAR proteins also function during viral infections and were shown to be either proviral or antiviral." (PMID 24586166, 2014). "During virus infections, the occurrence of inosines in RNA is by activation of the enzyme ADAR-1 (adenosine deaminase that acts on RNA-1)." (PMID 22028885, 2011). "The presence of Ino-RNA during virus infections requires activation of enzyme ADAR-1, a dsRNA-activated adenine deaminase." (PMID 22028885, 2011). "Next, we studied in detail the host-induced reaction to viral infection on a transcriptomic level, seeing that iPNs have an intrinsic expression of the core ISGs like ADAR, STAT1, STAT2, or CD47, which was confirmed with publicly available single-cell datasets." (PMID 39546567, 2024). "Given that ADAR expression was drastically altered in samples with viral infections, many of these processes may be altered in ways that cannot be linked to editing." (PMID 37968596, 2023). "Notably, ADAR-mediated A-to-I RNA editing has been reported as a key regulator of innate immune activation and antiviral activities during viral infections." (PMID 37081881, 2023). "Mechanistically, dysregulation of ADAR editing in vertebrates has been associated with cancer progression, autoimmune diseases, and increased inflammation, whereas during viral infection the pro- or antiviral role of ADAR hyper-editing depends on the host–virus combination." (PMID 35379005, 2022). "Adenosine-to-inosine (A-to-I) editing mediated by enzymes of the Adenosine Deaminase Acting on dsRNA (ADAR) family, produce posttranscriptional conversions in RNAs with double-stranded structures, a phenomenon relevant in natural and experimental viral infections." (PMID 35379005, 2022). "Alternatively, the changing pool of cellular RNAs during viral infection, through upregulation of endogenous retroelements or dysregulation of ADAR editing, might lead to a redistribution of cellular antiviral sensors." (PMID 34671803, 2022). "We call attention to the need for more research on virus–ADAR interactions in light of the role that viral-activated ADARs may play in pathogenesis, including the neurological consequences of viral infections." (PMID 34694399, 2021). "Finally, the possible role of adenosine deaminase acting on RNA (ADAR) must be taken into consideration, as these enzymes produce adenosine-to-inosine deamination in regions of the RNA, and play important roles during viral infections." (PMID 32438744, 2020). "As the role of ADAR as a controlling element in cellular response to viral infection is paramount, its regulation by MEG3 and interactions with lncRNAs in SARS-CoV-2 infected cells may influence progression of the disease." (PMID 33224264, 2020). "ADAR can be regarded as the ‘Editor-in-Chief’ of innate immunity against viral infection." (PMID 33224264, 2020). "Although most of the analyzed lophotrochozoans encode several ADAR paralogs, we demonstrated that only one ADAR gene is upregulated during viral infection in the bivalve C. gigas and in the gastropod H. diversicolor supertexta, and this gene refers to an ADAR1 paralog." (PMID 31337330, 2019). "In contrast, ADAR has an antiviral function in other virus infections." (PMID 24760760, 2014). "In some settings ADARs are inhibitory to virus infections whereas in other settings the presence of ADAR may promote virus infection." (PMID 23435233, 2013). "It's known that, during virus infection, ADAR activation leads to adenosine to inosine conversion." (PMID 22028885, 2011). "We have not found any particular relation between them; however, some of them might play a role in processes such as protein synthesis regulation in cardiomyocytes (PABPC1), cardiac differentiation and development (FURIN; ADAR), or cellular response to viral infection (TMED2)." (PMID 33917391, 2021).
viral infection (continued). "This study showed that during viral infection, the hDicer helicase binds to proteins that are involved in the antiviral response, such as DHX9, ADAR-1, and PKR kinase." (PMID 39695695, 2024). "ISGs products, including OAS1, OAS2, MX1, ADAR, and EIF2AK2, are major players in innate immune defence against viral infection." (PMID 36016774, 2022). "ADAR plays an important role in innate immunity against viral infection, and lncRNA MEG3 acts as the main regulator of ADAR." (PMID 36005145, 2022). "Next, the expression levels of ADAR and APOBEC enzymes responsible for A-to-I and C-to-U RNA editing during the course of virus infection were examined." (PMID 29363430, 2018). "Several interferon-inducible genes involved in immune response to viral infection (including OAS2, ISG15, STAT1, and ADAR) were identified as “drivers” in this sub-network based on the ARACNE and key driver analysis." (PMID 25868721, 2015). "Viral infection upregulated the expression level of an inosine writer, ADAR (also called ADAR1), observed in five out of six transcriptome experiments, while viral infection downregulated another inosine writer, ADARB1 (also called ADAR2), reported in one out of six experiments." (PMID 34502037, 2021). "A recent in vitro analysis showed significant ADAR genotype (and haplotype)-dependent modulation of IFNγ-producing cells (or IFNγ-Elispot responses upon viral infection) in CAs but not in AAs." (PMID 25868721, 2015).
melanoma (59 papers, 2014 to 2026). A malignant, usually aggressive tumor composed of atypical, neoplastic melanocytes. "Among Insoine modifying regulatory proteins strikingly, we found upregulation of ADAR in over 22% samples of melanoma." (PMID 31217906, 2019). "Not only increased ADAR expression but also gene silencing or deletion may contribute to tumor development, as reported in malignant melanoma and breast cancer." (PMID 41300768, 2025). "Another study demonstrated that ADAR promotes T-cell migration to human melanoma cells." (PMID 37414093, 2023). "We show here that the intratumoral level of ADAR, the gene that encodes adenosine deaminase specific for dsRNA, the major A-to-I editing enzyme, also positively correlates with the AEI and negatively correlates with survival time in melanoma." (PMID 37691856, 2023). "Similarly, the impairment of ADAR-mediated editing of miR-455-5p enhances the progression in melanoma." (PMID 34282776, 2021). "The silence of ADAR in mouse models can transform cold tumors into hot tumors by activating interferon-associated immunity in the tumor microenvironment, and reducing ADAR expression in tumors could increase sensitivity to checkpoint inhibitors in melanoma mouse models." (PMID 38203521, 2023). "The authors elegantly showed that peptides generated by ADAR-mediated A>I(G) RNA editing can be effectively presented and recognized by tumor-infiltrating CD8+ T cells in melanoma tumors." (PMID 39000531, 2024).
breast cancer (49 papers, 2015 to 2025). A primary or metastatic malignant neoplasm involving the breast. "Debora Fumagalli and colleagues reported an increase in ADAR mRNA and protein expression in breast cancer cell lines following interferon treatment." (PMID 38982182, 2024). "It should be noted that in breast cancer, ADAR-mediated RNA editing promotes tumor progression, whereas in hepatocellular carcinoma, ADAR1 contributes to increased cell proliferation by editing AZIN1 mRNA." (PMID 36556377, 2022). "The expression level of ADAR mRNA in different types of cancer tissues indicated that the expression level of ADAR in breast cancer tissues was also higher than that in other cancers." (PMID 34616451, 2021). "This study aims to investigate the expression characteristics of ADAR gene in breast cancer and to explore its role in the occurrence and development of BC and its possible mechanism." (PMID 34616451, 2021). "To evaluate the on-target effects of 8-chloroadenosine and 8-azaadenosine, we assessed the effects of each small molecule on cell viability of breast cancer cell lines previously identified to be ADAR-dependent or -independent." (PMID 35586115, 2021). "Subgroup analysis based on breast cancer subtypes, lymph node metastasis, histological subtypes, and individual cancer stages showed that ADAR mRNA levels in BC patients were significantly higher than those in normal tissues." (PMID 34616451, 2021). "The results of scratch assay showed that, in breast cancer cell lines, the scratch closure rate of inhibiting ADAR was significantly lower than that of the control group." (PMID 34616451, 2021). "Treatment of several breast cancer cell lines with 8-chloroadenosine led to reduced ADAR expression and induction of cell death." (PMID 35586115, 2021). "Compared with the control group in the confluence monolayer transwell experiment of cultured breast cancer cell line, si-ADAR inhibited the relative migration and invasion rate of ADAR." (PMID 34616451, 2021). "Correlation between ADAR copy number and ADAR expression has also been reported in breast carcinoma, ovarian adenocarcinoma, lung adenocarcinoma and liver carcinoma." (PMID 32410589, 2020). "ADAR gained the highest alteration frequency in breast cancer and was dominated by amplification." (PMID 37414093, 2023). "Recently, ADAR dependency was evaluated for a panel of human breast cancer cell lines." (PMID 35586115, 2021). "ADAR is significantly upregulated in breast cancer tissues, which may promote the progression of BC through the interaction of cancer cells, stromal cells, and immune cells." (PMID 34616451, 2021). "In addition, ADAR overexpression is connected with increased malignancy of breast, lung and liver cancer, and silencing of ADAR in breast cancer cells results in increased apoptosis." (PMID 32410589, 2020). "When taken in conjunction with reports of elevated ADAR activity in many breast cancers, it is feasible to assume that RNA editing could contribute to some of the characteristic phenotypic differences observed between these two cell lines." (PMID 30197877, 2018). "Targeting ADAR may offer new hope in treating breast cancer." (PMID 34616451, 2021). "In addition, we screened MEC1 cells for editing at sites recently described in a glioblastoma cell line and primary breast cancer samples, which revealed that many of these sites were also edited in MEC1 cells in an ADAR dependent manner." (PMID 32728184, 2021).
breast cancer (continued). "Despite the advances in the understanding of ADAR function in breast cancer, ADAR RNA editing functional consequences are not fully addressed." (PMID 30290838, 2018). "Finally, there are many types of breast cancer, and this study generally verified the function of ADAR in MCF-7 and ZR75-1 cells, without subdividing the types." (PMID 34616451, 2021). "Furthermore, a previous study had described ISG induction in the breast cancer cell line MCF-7 targeted by hnRNPC RNA interference, which could be mildly enhanced by ADAR targeting." (PMID 34297039, 2021).
hepatocellular carcinoma (38 papers, 2015 to 2025). A malignant tumor that arises from hepatocytes. "Previous studies have shown a significant correlation between increased ADAR expression and poorer survival outcomes in esophageal squamous cell carcinoma and human hepatocellular carcinoma." (PMID 36660243, 2023). "The association between the tumor aggressiveness and the overexpression of ADAR has also been demonstrated in hepatocellular carcinoma and colorectal cancer." (PMID 32410589, 2020). "This is potentially due to the fact that ADAR-mediated RNA editing isknown as a general suppressive mechanism to attenuate cellular dsRNA responses, inaddition to the intrinsically weakened dsRNA responses in hepatoma cells (39, –, 41)." (PMID 41070966, 2025).
gastric cancer (33 papers, 2016 to 2025). A primary or metastatic malignant neoplasm involving the stomach. "It has been verified by experiments that 8-azaadenosine can inhibit the proliferation of thyroid cancer cells and suppress the progression and peritoneal metastasis of gastric cancer by inhibiting ADAR." (PMID 37414093, 2023). "ADAR (an interferon-inducible RNA-editing enzyme) mitigates IFN signaling in gastric carcinoma through down-regulating STAT1 and IRF9 by miR-302a." (PMID 37408777, 2023). "Recent research studies have reported the role of ADAR in promoting gastric cancer, pancreatic cancer, thyroid cancer, and other cancers." (PMID 34616451, 2021). "Our data suggested that 8-Azaadenosine restrained proliferation of gastric cancer cells, indicating that targeting ADAR-mediated RNA editing could suppress gastric cancer progression." (PMID 35003354, 2021). "INHBA-AS1 upregulation in virus-infected cells may also contribute to cell survival through interaction with ADAR, as evidenced in gastric cancer and oral squamous cell carcinoma." (PMID 33224264, 2020). "Indeed, correlation analysis in gastric cancer patients from TCGA revealed a strong association in the expression of the two genes, suggesting that the regulation axis between TARDBP and ADAR could be functional in gastric cancer as well." (PMID 38773080, 2024).
glioblastoma (33 papers, 2017 to 2026). The most malignant astrocytic tumor (WHO grade IV). "Multiple malignancies, including hepatocellular carcinoma, chronic myelogenous leukemia, glioblastoma, and melanoma have aberrant ADAR activity and editing dysregulation." (PMID 36999050, 2023). "We show that the inosinome can superimpose another layer of information in lncRNAs, indicating, once more, that the ADAR enzymes are essential players in brain and glioblastoma." (PMID 33066171, 2020). "Together, these data suggest that ADAR3 binding to transcripts or editing regulators might alter recognition of the active ADAR enzymes for the same substrates, which leads to decreased editing of the glioblastoma transcriptome." (PMID 35850307, 2022). "In that report, deleterious GVs in the AGS genes ADAR and RNASEH2B were detected in families and patients with astrocytomas or glioblastomas as well as with prostate cancer." (PMID 41546701, 2026). "The de-regulation of ADAR-mediated RNA editing can promote cell transformation and tumor progression, and bioinformatic analyses combined with experimental studies have shown that ADAR-mediated editing patterns differ in normal and cancer tissues, including brain cancer, such as glioblastoma (GBM)." (PMID 33066171, 2020).
autoimmune disease (31 papers, 2015 to 2025). A disorder resulting from loss of function or tissue destruction of an organ or multiple organs, arising from humoral or cellular immune responses of the individual to their own tissue constituents. "Mutations in ADAR have been found in patients with Aicardi-Goutéres syndrome, an autoimmune disease characterized by brain inflammation due to increased IFN signaling." (PMID 34916907, 2021). "Regulation of RNA Pol III and thus Y RNA expression by ADAR1 provides also an unexpected piece to the puzzle of onset of autoimmune diseases such as systemic lupus erythematosus and Sjögren's syndrome in which the role of Ro60 and ADAR has been proposed." (PMID 38844344, 2024). "It should be noted that enrichment of ADAR SNP loci was identified in GWAS signals for autoimmune diseases." (PMID 34539640, 2021). "Three ADAR enzymes (ADAR1-3) are present in humans, albeit ADAR1 has been shown to play more significant roles in biological and pathological conditions, including infection, autoimmune disease and cancer." (PMID 29042669, 2017). "Dysregulation of ADAR activity may lead to a panoply of diseases, including autoimmune diseases, neurological diseases, cancer, cardiovascular diseases, and infectious diseases." (PMID 40852728, 2025). "Impairment of ADAR-mediated RNA editing activity has been associated with different neurological disorders, including ALS, epilepsy, Alzheimer's disease, autoimmune disorders, and ASD." (PMID 34916907, 2021).
colorectal cancer (21 papers, 2018 to 2026). A primary or metastatic malignant neoplasm that affects the colon or rectum. "In the present study, we aimed to investigate the relationship among transcript factors-microRNAs regulatory network, immune environment, and ADAR gene in colorectal carcinoma (CRC)." (PMID 36660243, 2023). "MEG3 was found to act as a biomarker and regulate cell functions by targeting ADAR in colorectal cancer." (PMID 33224264, 2020). "The cells overexpressing MEG3 exhibited increased ADAR expression, and downregulation of MEG3 was found in colorectal cancer tissues, cell lines and serum." (PMID 33224264, 2020).
lung carcinoma (21 papers, 2016 to 2026). "In the context of HCC, abnormal RNA editing and dysregulated ADAR expression have been associated with the development of lung cancer." (PMID 40852728, 2025). "In summary, we have identified ADAR loss as a genetic dependency in a subset of lung cancer cell lines which possess a high interferon gene expression signature." (PMID 30575730, 2018). "Overall ADAR-mediated RNA editing levels were ~2.9- and ~4.7-fold higher in healthy controls than in colorectal and lung cancers, respectively." (PMID 41898488, 2026). "Although most ADAR editing occurs in non-coding regions in lung cancer, few studies have shown the crosstalk between ADAR and non-coding RNAs." (PMID 32316322, 2020). "In cancer cells with elevated ADAR-mediated RNA editing, such as breast and lung cancers, downregulation of ADAR expression reduces their tumorigenic capacity." (PMID 30619092, 2018). "We find that lung cancer cell lines expressing high levels of interferon-stimulated genes (ISGs) are vulnerable to deletion of the RNA adenosine deaminase, ADAR or ADAR1." (PMID 30575730, 2018). "Our data show that MDA5/MAVS signaling is not essential for ADAR genetic dependency in lung cancer cell lines." (PMID 30575730, 2018).